UBXN7 (UBX domain protein 7)
Description:
Ubiquitin-binding adapter that links a subset of NEDD8-associated cullin ring ligases (CRLs) to the segregase VCP/p97, to regulate turnover of their ubiquitination substrates.
Synonyms: KIAA0794; UBXD7
Tractability: PROTAC: UniProt records ubiquitination sites on it; ubiquitination databases record sites on it; its protein half-life has been measured.
Gene: Protein-coding gene on chromosome 3 (196,347,659 to 196,432,430, reverse strand). Ensembl gene ENSG00000163960.
Subcellular location: Nucleus
Subcellular location (Human Protein Atlas): Nucleoplasm
Pathways (Reactome):
Cellular responses to stimuli: KEAP1-NFE2L2 pathway
Metabolism of proteins: Neddylation
Gene Ontology:
Molecular function: protein binding; RNA polymerase II-specific DNA-binding transcription factor binding; ubiquitin binding; ubiquitin protein ligase binding
Biological process: proteasome-mediated ubiquitin-dependent protein catabolic process
Cellular component: nucleoplasm; VCP-NPL4-UFD1 AAA ATPase complex; ATPase complex; cytosol; nucleus
Genetic constraint (gnomAD): Loss-of-function variants: 9 observed, 56.88 expected, observed/expected ratio (o/e) 0.16, 90% interval 0.094 to 0.28. The upper end of that interval is the gene's LOEUF score, 0.28, which puts it in group 1 of 6, group 1 being the genes least tolerant of losing a copy. Missense variants: 325 observed, 618.47 expected, observed/expected ratio (o/e) 0.53, 90% interval 0.48 to 0.58. Synonymous variants: 207 observed, 215.15 expected, observed/expected ratio (o/e) 0.96, 90% interval 0.86 to 1.08.
Homologues: Orthologues: chimpanzee UBXN7 (100% identical), macaque UBXN7 (99% identical), mouse Ubxn7 (98% identical), rat AABR07034438.1 (98% identical), tropical clawed frog ubxn7 (77% identical), zebrafish ubxn7 (75% identical). Paralogues in human: FAF1 (18% identical), FAF2 (17% identical), UBXN8 (10% identical), UBXN10 (9% identical).
Diseases named in the same sentence as UBXN7 in open-access papers:
UBXN7 is named in the same sentence as 8 diseases in open-access papers, as found by Europe PMC text mining. Sharing a sentence is not in itself a finding about the gene and the disease. The quoted sentences say what the papers report.
bladder cancer (1 paper, 2019). "Due to its high stability, circRNA is an excellent biomarker for human diseases, especially cancer; examples include circ-SMARCA5 as a biomarker for hepatocellular carcinoma, circ-ANKS1B for breast cancer, circ-UBXN7 for bladder cancer and circ-LMTK2 for gastric cancer." (PMID 31631067, 2019).
heart failure (1 paper, 2022). Inability of the heart to pump blood at an adequate rate to meet tissue metabolic requirements. "UBXN7 was upregulated in human epicardial adipose tissue samples from patients with heart failure." (PMID 36313450, 2022).
tumour (1 paper, 2024). "Most tumour tissues showed moderate nuclear positivity in the UBXN7 protein, and a small number of skin cancers and rare tumours of the ovary, cervix, lung, and testicle are strongly positive." (PMID 38365777, 2024).
UBXN7 also shares sentences with these, for which no sentence is quoted: cancer (2 papers); breast carcinoma (1); gastric cancer (1); hepatocellular carcinoma (1); Obesity (1).